PLK1 (polo like kinase 1)
Diseases named in the same sentence as PLK1 in open-access papers (continued):
Sharing a sentence is not in itself a finding about the gene and the disease.
tumor (continued). "This PLK1‐based immune risk model can effectively predict the prognosis and tumor progression of BRCA, identify gene mutations, and evaluate patient's response toward immunotherapy and chemotherapy regimens." (PMID 36951624, 2023). "In recent years, it has been suggested that increased levels of PLK1 and its activity are associated with tumor progression and poor prognosis." (PMID 36805592, 2023). "siRNA induced Plk1 gene knockdown significantly inhibited the bioactivity of endogenous Plk1 gene and cause obvious ablation of tumor, therefore achieved MRI-guided gene therapy and photothermal therapy." (PMID 34466734, 2022). "As detailed above, activation of specific signaling pathways that promote tumor cell proliferation, cell cycle progression, or oncogenesis, such as Erk1/2, Pin1 and PLK1, have been associated with FBXW7 auto-ubiquitination and degradation." (PMID 35346215, 2022). "Cell proliferation–related genes, including Mki67, Cdk1, Plk1, and Ccnb1, were downregulated in tumor-infiltrating SENP7-deficient CD8+ T cells." (PMID 35143421, 2022). "The use of PLK1 inhibitors to induce toxicity in tumor cells with loss of FBXW7 has been reported in many studies." (PMID 35346215, 2022). "We further showed that overexpression of SETD3 promoted tumor cell proliferation and migration, whereas inhibition of PLK1 activity attenuated these phenotypes caused by SETD3." (PMID 35912180, 2022). "Plk1 is a serine/threonine kinase that plays great roles in the progression and withdrawal of mitosis and is implicated in tumour development." (PMID 36499653, 2022). "The expression of PLK1 has been observed to be higher in PCas than in the adjacent normal tissue, and its expression levels are linked with tumor grades." (PMID 34775484, 2022). "In digestive system neoplasms, PLK-1 overexpression was significantly associated with histopathological classification, primary tumor grade, histological grade, and clinical stages (p = 0.002, p = 0.001, p < 0.0001, respectively)." (PMID 36457496, 2022). "Small interfering RNA, CRISPR/Cas9 deleted PLK1 and chemical inhibitors of PLK1 have an impact on cell proliferation, cause mitotic arrest, cell death and in vivo tumor growth inhibition." (PMID 35719948, 2022). "Treatment of PLK1 inhibitor caused reduced AR protein level and inhibited tumor growth in LNCaP CRPC xenografts." (PMID 36098827, 2022). "Targeting and knocking out of PLK1 has been found to cause the TNBC tumor cells to be arrested in the G2-M cell cycle." (PMID 36407327, 2022). "In colon cancer with chromosomal instability due to a non-sense APC mutation, elevated PLK1 levels have tumor-suppressive potential and increase the survival of patients." (PMID 34065956, 2021). "This study showed that aberrant activation of PLK1 signaling, which causes a dysfunctional cell cycle, was correlated with poor prognosis and tumor recurrence in CRC." (PMID 34881526, 2021). "Again, c-ABL mediated phosphorylation of PLK1 was associated with a worse 5-year survival rate, while PLK1 mutant Y425 partially inhibits tumor growth in mice." (PMID 34830902, 2021). "We show that MYC activates PLK1 transcription, while the inhibition of PLK1 suppresses MB tumor development and causes a decrease in c-MYC protein level by suppressing FBXW7 auto poly-ubiquitination." (PMID 33494392, 2021). "Previous studies have shown that the PLK1 protein interacts with multiple tumor suppressors to cause tumorigenesis and that targeting the protein can improve the sensitivity of tumors to chemoradiotherapy." (PMID 33304656, 2020). "PLK1 has also been shown to be associated with tumor epithelial-mesenchymal transition and tumor invasion." (PMID 32518522, 2020). "This is despite many pre-clinical studies showing PLK1 inhibition reduces tumor growth in various cell line-based models and accumulated evidence, showing that PLK1 inhibition can cause lethality in TICs." (PMID 33066048, 2020).
tumor (continued). "Concomitantly, any tumoral tissue is susceptible to express high levels of Plk1 as a mere reflection of its higher proliferation rate." (PMID 30862113, 2019). "PLK1 overexpression has been observed in a wide range of tumor types and is often associated with a poor prognosis including lung cancer." (PMID 30367032, 2018). "High expression of polo‐like kinase‐1 (PLK1), a protein which has multiple functions during mitosis, has been associated with poor prognosis in several tumor types." (PMID 28766886, 2017). "In an effort to identify novel tumor dependencies, we performed a loss-of-function screen targeting ≈500 kinases and identified polo-like kinase 1 (PLK-1)." (PMID 29383095, 2017). "Among the 30 MPNST samples, a high level of PLK1 expression was associated with large tumor size and high tumor grade." (PMID 28556483, 2017). "In this context, aptamer targeting EpCAM was shown to inhibit CSCs when linked to siRNAs against PLK1, a kinase required for mitosis, and cause tumor regression when injected in the TNBC xenograft model." (PMID 28974015, 2017). "Using a small-molecule kinase inhibitor screen, PLK1 was identified as a critical regulator of survival and self-renewal in NB tumor-initiating cells that have been implicated in sustaining tumor growth, progression and metastasis." (PMID 26046302, 2016). "Our work demonstrates that inhibiting selective members of the PP2A complex has the potential to mitigate tumor heterogeneity associated with PLK1 overexpression." (PMID 27557495, 2016). "By contrast, deficiency of p21 renders tumor cells more susceptible to Polo-like kinase 1 inhibition by showing a pronounced mitotic arrest, DNA damage and apoptosis." (PMID 25483104, 2015). "Accordingly, downregulation of PLK1, associated with caspase-3 cleavage, was only found in lysates from CaSki tumor xenografts, grown sc in mice, after a single dose of CPT11." (PMID 25826089, 2015). "The overexpression of PLK-1 is actively implicated in the failure of mitotic checkpoint arrest and tumor progression." (PMID 26557691, 2015). "Fisher’s test of association between tumour periphery (TP) polo-like kinase 1 (PLK1) scores and clinicopathological variables." (PMID 26047016, 2015). "PLK1 is considered a proto-oncogene, whose overexpression is often observed in tumor cells and FBXW7α is a tumor suppressor whose mutation occurs in multiple neoplasms." (PMID 24970797, 2014). "Decreased prostate carcinogenesis in SPDEF-deficient mice was associated with decreased proliferation of tumor cells and reduced expression of Cdc25b, Cyclin B1, Plk-1, AuroraB, and Topo2alpha, factors that are critical for tumor cell proliferation." (PMID 25254494, 2014). "Plk1 was found overexpressed in a variety of human tumors and its expression was associated with cellular proliferation and prognosis of tumor patients." (PMID 25265536, 2014). "PLK1 is highly expressed in numerous tumor tissues or cells and is associated with clinical stage, metastasis and invasiveness, as well as with the prognosis of patients with tumors." (PMID 23226764, 2012).
tumor (continued). "Inhibition of PLK1 leads to mitotic arrest, interruption of cytokinesis, and apoptosis in susceptible tumor cell populations." (PMID 22309939, 2012). "Expression levels of Mcm2, geminin, Plk1, Aurora A and H3S10ph were strongly associated with tumour grade." (PMID 19240714, 2009). "Furthermore, the significant association between high PLK1 expression and an immunosuppressive tumor microenvironment was confirmed by ssGSEA." (PMID 41556056, 2026). "Notably, KI-AA1524/CIP2A also interacts with several phosphorylated PP2A substrates involved in tumor growth, including c-Myc, polo-like kinase 1 (Plk1), E2F1, Akt, and death-associated protein kinase 1 (DAPK1)." (PMID 41154660, 2025). "In contrast, CHEK1 and PLK1 are cell cycle regulators, whose high expression is associated with enhanced tumor cell proliferation, offering a molecular explanation for the poorer prognosis and potentially reduced responsiveness to conventional immunotherapies in the high-risk group." (PMID 41278297, 2025). "Like most cell cycle-associated proteins, PLK1 is differentially expressed in tumor cells." (PMID 40486867, 2025). "Therefore, this review focuses on the applications and underlying mechanisms of PLK1 in tumor immunotherapy, aiming to provide new insights for improving patient outcomes and prognosis." (PMID 40612941, 2025). "Together, these findings suggest that damaging mutations in the FA pathway and associated genes may predict tumor response to PLK1-targeting agents." (PMID 40111122, 2025). "The phosphorylation states of PDK1 and PLK1 are closely linked to metabolic reprogramming, suggesting that dynamic kinase modifications may underlie tumor heterogeneity in iCCA." (PMID 41296409, 2025). "Systemic targeting of PLK1 may cause “on-target, off-tumor” toxicity, leading to bone marrow suppression or gastrointestinal injury." (PMID 40612941, 2025). "We show that high PLK1 is associated with lower infiltrating T cells and NK cells, and this feature may be harmful to anti-tumor response in LUAD." (PMID 38885192, 2024). "Hence, the promising single agent activity observed with intermittent IV schedules is associated with prolonged tumor TTK target occupancy combined with transient PLK1 occupancy." (PMID 39184047, 2024). "Moreover, intermittent intravenous single-agent BAL0891 treatment of the MDA-MB-231 mouse model of TNBC induced profound tumor regressions associated with prolonged TTK and transient PLK1 in-tumor target occupancy." (PMID 39184047, 2024). "Moreover, it was also found in mice with glioblastoma and injected with CRISPR-LNP targeting PLK1, an enzyme essential for cell division, which successfully caused apoptosis in tumor cells after editing the gene encoding this enzyme within the tumor cells." (PMID 37183261, 2023). "Meanwhile, Plk1 (mouse ortholog of PLK1) in tumor tissue was increased on both mRNA and protein levels, strongly suggesting that the loss of inhibition from mus-miR-100-5p could greatly impact Plk1 expression." (PMID 38201556, 2023). "Therefore, the loss of PLK1 or pharmacological inhibition of PLK activity resulted in slower cell proliferation concomitantly with spindle checkpoint blockade and G2/M phase arrest in tumor cells." (PMID 37730838, 2023). "Therefore, further research is needed to explore the molecular mechanisms underlying the anti-tumor effects of targeting PLK1." (PMID 37744268, 2023). "Therefore, the association between PLK1 gene expression levels and tumor microenvironment was analyzed." (PMID 36618405, 2022). "Consequently, this caused a marked delay in xenograft tumour growth in mice treated with the PLK-1 inhibitor BI2536, with a lower mean tumour volume compared with the control group." (PMID 34445233, 2021).
tumor (continued). "Thus, we can stratify patients into high-risk groups and rapidly assess their outcomes based on the tumor expression of cytoplasmic PLK1, phosphoMet, SGK2, and SHC1." (PMID 34575686, 2021). "Thus, PLK1 coordinates the activity of EBNA2 to attenuate the risk of tumor incidences in favor of the establishment of latency in the infected but healthy host." (PMID 34605140, 2021). "Dysfunction of these interactions could be associated with the overexpression of Plk1 and its capacity to induce tumor development." (PMID 34646387, 2021). "PLK1 expression was associated almost exclusively with tumor grade." (PMID 33313822, 2021). "The siRNA of Polo-like kinase 1 (PLK1) (more than 90%) would be only released after a two-step decomposition caused by acidic pH and esterase in the tumor area, which efficiently inhibited ~70% of PLK1 expression and around 2-fold of MDA-MB-231 tumor growth within 18 days." (PMID 32328480, 2020). "Besides, The Cancer Genome Atlas (TCGA) analysis revealed that PLK1 was elevated in tumor tissues and associated with short survival in patients with OSCC." (PMID 31387297, 2019). "Furthermore, we explored the potential mechanisms that underlie the significant associations between PLK1 expression and tumor immunity." (PMID 30631355, 2018). "Furthermore, we explored the mechanism underlying the significant associations between PLK1 and tumor immunity." (PMID 30631355, 2018). "For instance, Plk1(+/−) mice display increased susceptibility to spontaneous tumor development." (PMID 30069007, 2018). "BI 6727 is a highly effective PLK1 inhibitor, causing tumor regression in our ATRT model." (PMID 29228610, 2017). "As PLK1 overexpression induces gain or loss of chromosomes, we expect that PLK1 overexpression can be used as a model to capture the heterogeneous tumor population." (PMID 27557495, 2016). "Considering our current findings, abrogation of Plk1 phosphorylation site in this BRCA1 variant could very likely participate in the disruption of BRCA1 function in the tumor." (PMID 26745677, 2016). "In contrast, cells without p21 displayed a pronounced mitotic arrest, irreversible DNA damage, the activation of apoptosis favorable MAPK/Erk pathway and intense apoptosis induction, strongly indicative of a high efficacy of Plk1 inhibitors in p21-deficient tumor cells." (PMID 25483104, 2015). "Paradoxically, loss of Plk1 is also associated with tumor formation." (PMID 19161615, 2009). "However, Plk1 overexpression has been indicated as the cause of tumor formation instead of being the consequence of high mitotic index during tumor cell proliferation." (PMID 19161615, 2009). "Conversely, the association between high PLK1 expression and an immunosuppressive tumor microenvironment, as demonstrated in our data, suggests that PLK1 inhibitors might synergize with immunotherapies in immune-“cold” subtypes, such as those with STK11 mutations." (PMID 41556056, 2026).
tumor (continued). "Finally, acquired mutations in the ATP-binding domain in tumor cells, such as Gatekeeper mutations in the kinase domain, may lead to decreased drug-binding affinity for PLK1 inhibitors and thus the phenomenon of acquired resistance." (PMID 40612941, 2025). "Among seven potential tumor-suppressing miRNAs identified in this study, high expression of miR-100 was associated with better outcomes in women with luminal A tumors treated with adjuvant endocrine therapy and was inversely linked to mRNA expression of PLK1, FOXA1, mTOR, and IGF1R." (PMID 37508580, 2023). "Therefore, we analyzed the correlation between tumor mutation burden and the expression of targets, and the results showed that the expression of AURKA, CCNA2, CCNE1, CDK1, CHEK1, and PLK1 were significantly positively correlated with the tumor mutation burden." (PMID 36483630, 2022). "Therefore, the R293C/H missense mutation of PLK1 may serve as a new potential direction for tumor research in the future." (PMID 36618405, 2022). "Furthermore, studies have demonstrated that overexpressed level of PLK-1 is not only associated with tumor progression but it may also lead to drug resistance." (PMID 28415805, 2017). "Indeed, the ectopic expression of PLK1 is associated with a wide range of tumor types." (PMID 29254517, 2017). "In LUAD patients, tumor tissues demonstrated significantly elevated PLK1 expression compared to adjacent normal tissues." (PMID 41556056, 2026). "Single-cell and spatial transcriptomic approaches were employed to map PLK1 expression heterogeneity and its precise localization within tumor architecture." (PMID 42205755, 2026). "PLK1 expression was significantly elevated in LUAD tumor tissues compared to adjacent normal samples across multiple cohorts." (PMID 41556056, 2026). "PLK1 mRNA expression was markedly elevated in the tumor tissues versus adjacent normal tissues from EGFR-mutant NSCLC patients." (PMID 41539998, 2026). "Validation using the GSE115002 dataset (52 paired samples) confirmed higher PLK1 levels in tumor tissues (p < 0.001)." (PMID 41556056, 2026). "Our preclinical study found that the combination of the PLK1 inhibitor volasertib with the EGFR-TKI osimertinib induced complete tumor regression in EGFR-mutant NSCLC xenograft models, with sustained effects observed even after treatment cessation." (PMID 41539998, 2026). "Elevated PLK1 expression maintained predictive value across tumor stages—T2 (HR = 2.18, p < 0.001), N0 (HR = 2.29, p < 0.001), and M0 (HR = 2.05, p < 0.001)—as well as pathological stages I–III (HR = 1.93, p < 0.001)." (PMID 41556056, 2026). "Analysis of clinical databases revealed that PLK1 mRNA expression is more markedly elevated in tumor tissues than in adjacent normal tissues from EGFR-mutant NSCLC patients." (PMID 41539998, 2026). "Expression of PLK1 (polo like kinase 1) was the most predictive gene regarding survival and tumor evolution." (PMID 41596231, 2026). "Single-cell and spatial transcriptomic analyses showed that PLK1 expression was enriched in malignant epithelial cells and proliferative tumor regions and displayed marked intratumoral heterogeneity." (PMID 42205755, 2026).